RNU6-713P (RNA, U6 small nuclear 713, pseudogene)
Gene: Small nuclear RNA gene on chromosome 12 (40,554,161 to 40,554,267, reverse strand). Ensembl gene ENSG00000207492.
Homologues: Orthologues: chimpanzee U6 (99% identical), macaque U6 (93% identical), dog U6 (86% identical), mouse Gm24378 (77% identical), rat LOC120097314 (74% identical). Paralogues in human: RNU6-1060P (90% identical), RNU6-116P (88% identical), RNU6-15P (88% identical), RNU6-19P (88% identical), RNU6-949P (88% identical), RNU6-12P (87% identical), RNU6-13P (87% identical), RNU6-21P (87% identical), RNU6-31P (87% identical), RNU6-32P (87% identical), RNU6-33P (87% identical), RNU6-345P (87% identical), and 1287 more.